LEP (leptin)
Diseases named in the same sentence as LEP in open-access papers (continued):
Sharing a sentence is not in itself a finding about the gene and the disease.
Obesity (continued). "With SOCS3 role as a prominent negative regulator of both leptin and insulin signaling, it has been implicated in the pathogenesis of obesity as well as associated metabolic abnormalities." (PMID 27472371, 2016). "Resistance to the actions of leptin or insulin is associated with the pathophysiology of obesity and type 2 diabetes." (PMID 27812350, 2016). "Obesity in this population is likely linked to hypothalamic dysfunction, and a result of hyperphagia, hyperleptinemia or reduced leptin sensitivity, and/or low sympathetic or dopaminergic tone." (PMID 26937243, 2016). "Frequent association of obesity with clinical depression can be explained by the impaired leptin activity in brain." (PMID 26886906, 2016). "Leptin and insulin are present in the hypothalamic neurons that are involved in body weight regulation, and the loss of leptin and insulin in the hypothalamus can promote obesity and type 2 diabetes." (PMID 27375435, 2016). "Elevated SOCS-3 expression in the CNS is proposed to be the primary mechanism that causes leptin resistance and subsequent failure in controlling food intake in obesity." (PMID 27716333, 2016). "Congenital leptin deficiency in both mice and humans results in early obesity due to severe hyperphagia, but can be corrected with leptin replacement therapies." (PMID 27379019, 2016). "Collectively, these findings demonstrate that obesity in BBS arises from leptin resistance in association with disrupted trafficking of the LRb to the plasma membrane." (PMID 26926121, 2016). "Both leptin and insulin resistance in myocytes are associated with the onset of obesity, type 2 diabetes, and other metabolic disorders." (PMID 27746742, 2016). "Dysregulation in leptin metabolism has been linked to obesity, hyperinsulinemia and diabetes mellitus." (PMID 27636369, 2016). "Increased peripheral chemosensitivity (PChS) has been proposedas mechanism underlying obesity-related sympathoactivation, with insulin and/or leptin as possible mediators." (PMID 26781642, 2016). "For example, leptin-deficient ob/ob mice are characterized not only by hyperphagia and obesity, but also mild hypothermia when housed at room temperature, and they become profoundly hypothermic when exposed directly to cold environments." (PMID 27689002, 2016). "Leptin dysregulation has been postulated to affect cancer risk through its effects on obesity and inflammation." (PMID 27636369, 2016). "Specifically, loss of leptin signaling in SF-1 neurons in the VMH resulted in diet induced obesity due to impaired energy expenditure and increased food consumption." (PMID 27598259, 2016). "Obesity was recently associated with hypermethylation of gene loci involved in inflammation, insulin signaling, and leptin signaling in normal breast tissue from cancer-free women." (PMID 27338371, 2016). "As leptin has long been linked with obesity, recent studies have depicted the role of leptin in T2DM and insulin resistance." (PMID 27195302, 2016). "It has been demonstrated that human obesity in children and adults is associated with elevated serum levels of an adipokine, the hormone leptin, reflecting the amount of energy stored in adipose tissue." (PMID 27440187, 2016). "Reduced expression of both of these genes has been demonstrated to cause obesity and impaired glucose homeostasis, and at least partially mediates obese phenotypes in leptin-deficient mice." (PMID 27832201, 2016). "Both leptin and kisspeptin were associated with obesity-related parameters and exhibited the significant gender-based differences in circulating concentrations." (PMID 27990162, 2016). "Alternate mechanism indicating obesity leading to increased leptin levels which stimulate hypothalamus causing increased TRH secretion has also been proposed." (PMID 27478827, 2016).
Obesity (continued). "The precise molecular mechanisms of cereal fiber on leptin resistance and sensitivity in-depth remain to be elucidated, in order to promote the proof that cereal fiber prevents obesity-associated diseases." (PMID 27534844, 2016). "Mutations in leptin or leptin receptor genes result in severe obesity phenotypes in both humans and rodents." (PMID 26849804, 2016). "In humans, genetic leptin deficiency also causes severe obesity, though leptin and leptin-receptor-related mutations are extremely rare." (PMID 27716333, 2016). "HFD-induced obesity is also known to be strongly associated with the levels of adipokines such as leptin and adiponectin, both of which are secreted from adipose tissue." (PMID 26630290, 2015). "It is now two decades since the discovery of defects in Lep and Lepr in the mouse models ob/ob and db/db respectively led to the discovery of the first monogenic obesity syndromes, leptin and leptin receptor deficiency, in humans." (PMID 26120850, 2015). "Obesity has been associated with higher plasma concentration of leptin and lower plasma concentration of ADIPOQ in horses." (PMID 25938677, 2015). "Mutations in leptin, leptin receptor, and the central melanocortin system are the most common mutations in the monogenic form of obesity in humans." (PMID 26236282, 2015). "The results showed that apart from the high circulatory leptin that is present in an underlying condition of obesity, a progressive phase of NASH is accompanied by an even higher leptin in the liver." (PMID 25658689, 2015). "Leptin is associated with obesity and is a potential contributor to many of the cardiovascular risks linked to obesity." (PMID 26064110, 2015). "A low adiponectin level has been reported to be correlated with obesity, MetS, and CVD, while a high leptin level has been indicated to be associated with CVD that has close relation to obesity." (PMID 25628655, 2015). "Disruption of LepRb selectively in PrRP neurons blocks thermogenic responses to leptin and causes obesity in mice." (PMID 26379628, 2015). "Leptin administration has been demonstrated to reduce obesity in leptin-deficient ob/ob mice and, to decrease food intake, body weight, increase energy expenditure and improve metabolic status in leptin deficient subjects." (PMID 26581745, 2015). "The daily subcutaneous injections of recombinant leptin led to a reduction of hyperphagia and body weight in children with the severe obesity caused by inactivating mutations in the gene encoding leptin." (PMID 28031898, 2015). "Obesity is associated with high levels of the circulating hormone leptin (hyperleptinemia), which in turn is responsible for several cardiovascular diseases." (PMID 26557089, 2015). "Primary outcomes were obesity-associated hormones relevant to oesophageal adenocarcinoma risk (circulating concentrations of leptin, adiponectin, interleukin-6, tumour necrosis factor-alpha, C-reactive protein, and insulin resistance [HOMA])." (PMID 25706622, 2015). "Several specific inflammatory factors have been linked to both obesity and AD including leptin, TNF-α and IL-6." (PMID 26217222, 2015). "Rodent models for T2D, such as the Lepob and Zucker mice strains rely on the mutations in genes encoding leptin or its receptor to develop T2D via obesity." (PMID 26363598, 2015). "One of the mechanisms proposed to explain the association between obesity and cancer risk is the potential action of adipokines (e.g., leptin, adiponectin, insulin growth factor-1 (IGF-1)) on tumor tissue." (PMID 25857300, 2015). "Although an increased leptin level is positively associated with obesity and cancer risk, detailed molecular mechanisms underlying are not clearly understood." (PMID 25704884, 2015). "Obesity is associated with elevations in insulin, free insulin-like growth factors (IGFs), and adipocyte-derived factors that include leptin, TNF-alpha, IL-6, and reductions in adiponectin." (PMID 25811460, 2015).
Obesity (continued). "Adiponectin and leptin have been reported to play roles in obesity as well as obesity-associated diseases such as cardiovascular disease, type-2 diabetes, and cancer, including breast cancer." (PMID 26132992, 2015). "Data from human studies indicates that low maternal concentrations of plasma leptin increases risk of obesity in offspring." (PMID 26561832, 2015). "High circulating levels of leptin associated with obesity can induce leptin resistance, diminished responsiveness to leptin and decreased leptin levels in the brain." (PMID 26580647, 2015). "Sleep disturbances and, particularly, deprivation are associated with an increased risk of obesity, diabetes and insulin insensitivity, and dysregulation of leptin and ghrelin, which negatively impact human health." (PMID 25861266, 2015). "In mouse studies, besides feeding wild-type mice ad libitum with a high-fat diet, leptin-deficient (ob/ob) mice have also been used as a model for obesity." (PMID 25561744, 2015). "Obesity is associated with leptin resistance, cardiometabolic alterations and a pro-inflammatory status." (PMID 25897330, 2015). "The relationship between the decrease in leptin sensitivity in the brain and the development of insulin resistance was shown in patients with obesity, MS and T2DM having the Gln223Agr and Asp100Tyr mutations in gene encoding leptin receptor OBRb." (PMID 28031898, 2015). "It has been reported that cannabinoid receptor type 1 (CB1) agonism ensures palatable food consumption, while the antagonism for CB1 induces weight loss in obesity status possibly improving leptin sensitivity at central level." (PMID 25960740, 2015). "In the future, to distinguish between differences due to IR versus leptin deficiency, it would be interesting to apply our method to other mouse models of IR, such as diet-induced obesity." (PMID 25840986, 2015). "Genes underlying highly penetrant forms of monogenic obesity are part of the leptin-melanocortin pathway in the hypothalamus." (PMID 25825681, 2015). "Majority of studies have documented a significant relationship between higher leptin concentrations and an increased risk of obesity, hypertension, metabolic syndrome as well as markers of inflammation and thrombophilia." (PMID 26388952, 2015). "While there are a variety of pathways that can lead to obesity, perhaps the best characterized are the aberrant feeding behaviors associated with alterations in the leptin/leptin receptor pathway." (PMID 25856311, 2015). "Further leptin has been implicated in endothelial dysfunction of obesity and neovascularization in NASH." (PMID 25658689, 2015). "One of the stronger features associated with obesity is the significant increase of leptin production." (PMID 26190966, 2015). "Recent studies on the development of obesity in male Wistar rats uncovered an association of diet-induced fatty liver (steatosis) with insulin/leptin resistance." (PMID 26694100, 2015). "Taken together, our study once again illustrates bioinactivity of leptin as a cause of pharmacologically treatable, early-onset, severe obesity." (PMID 26186301, 2015). "We were also unable to study the effect of adipokines, such as leptin and adiponectin, which have been linked to poor sleep quality and obesity." (PMID 26568665, 2015). "High circulating leptin levels have been associated with obesity and insulin resistance, reflecting a state of leptin resistance." (PMID 25834745, 2015). "Diet-induced obesity caused by intake of a chronic high-fat diet mainly induces cellular leptin resistance in the ARC and the ventral tegmental area, but not in the lateral hypothalamus, ventromedial hypothalamus, and dorsomedial hypothalamus." (PMID 26236282, 2015). "Our results showed a clear association between leptin mRNA expression and adipocyte size (a marker of obesity) in patients with EAC." (PMID 25857300, 2015).
Obesity (continued). "Obesity leads to decreased level of circulating adiponectin and increased level of insulin-like growth factor 1 and leptin, which contribute to an increased risk of colorectal cancer." (PMID 26467912, 2015). "Taken together, in the present study, circulating levels of leptin are found to be associated with well defined cardiovascular risk factors such as obesity, triglycerides, insulin and TNF-α in AMI subjects." (PMID 25762868, 2015). "Levels of plasma leptin correlate with total body fat stores, being elevated in obesity and reduced in weight loss." (PMID 26770217, 2015). "Literature data suggest that the ADPN/LEP ratio is a sensitive risk indicator of metabolic syndrome in patients with overweight and obesity." (PMID 26389928, 2015). "The ability of leptin to regulate appetite and energy expenditure in rodents with subsequent loss of adipose tissue has led to the description of leptin as an anti-obesity hormone." (PMID 26636332, 2015). "The development of leptin resistance, hyperphagia, and increased adiposity cause increases in the risk of adult obesity." (PMID 26825664, 2015). "The association obesity-endothelial dysfunction involves several mechanisms that include increased plasma leptin levels." (PMID 26381906, 2015). "The increase in visceral fat is associated with insulin resistance, whereas subcutaneous fat is more strongly associated with circulating concentrations of leptin and with general obesity." (PMID 25648854, 2015). "Leptin is an adipokine produced by the adipose tissue, and it is proposed to be one of the associates between obesity, insulin resistance, and PCOS." (PMID 26180527, 2015). "Disruption of signaling capacity of leptin associated with obesity is a potential risk factor leading to pregnancy complications as a result of fuel partitioning in utero." (PMID 25874125, 2015). "It has been suggested that resistance to leptin produce metabolic and inflammatory alterations in several tissues and organs, including the liver, spleen and heart, therefore leptin resistance contributes to the risk for obesity-related comorbidities." (PMID 25897330, 2015). "Using a keyword search, we found literature data showing that the leptin deficiency is a biochemical marker of obesity, whereas leptin overexpression can serve as a marker of obesity-caused hypertension." (PMID 26694100, 2015). "These SNPs are also associated with obesity-related anthropometric traits such as fat mass, leptin levels and waist-to-hip ratio, as well as an increase in food intake and a reduction in satiety." (PMID 25830092, 2015). "Obesity-associated increase in the production of leptin (pro-inflammatory) and decrease in adiponectin (anti-inflammatory) modify the activation of immune cells." (PMID 25826263, 2015). "In general, leptin, as a factor causing obesity, is affected by several factors such as steroid therapy, CRT, chemotherapy, and resistance to central leptin." (PMID 26705449, 2015). "Adiponectin is anti-inflammatory, and is inversely associated with obesity and other parameters of MetS; leptin, on the other hand, is positively correlated with obesity, playing a key role in regulating body mass." (PMID 26418011, 2015). "Defective leptin signaling, due to either leptin deficiency or mutations in the leptin receptor, leads to the development of obesity." (PMID 26493717, 2015). "Diet-induced obesity causes central leptin resistance first by affecting the central access of leptin and later by causing leptin resistance within the central nervous system." (PMID 26236282, 2015). "Leptin plays a critical role in the hypertension associated with obesity, and several studies suggest that this is tied to activation of the ET-1 system via increased signaling at the ETA receptor." (PMID 26569331, 2015). "Up to 10% of patients develop stones or sludge over the course of each pregnancy, obesity and increased leptin being risk factors." (PMID 25628906, 2015).
Obesity (continued). "Breastmilk leptin has been the most widely studied appetite hormone, and a strong association between breastmilk leptin and a reduced risk of developing obesity later in life has been shown." (PMID 26437426, 2015). "The results from this study confirm that obesity is associated with cardiometabolic alterations, leptin resistance and a pro-inflammatory status." (PMID 25897330, 2015). "Obesity associated genes such as leptin, FAS, adiponectin, transcriptional factors (PPARs-α, γ, δ, SREBPs, C/EBPs) regulate adipogenesis and lipid metabolism at various stages of adipocyte differentiation." (PMID 25887331, 2015). "Identification of leptin gene mutations and treatment of obesity with recombinant leptin were milestone developments in the biomedical research of obesity and confirmed for the first time that single gene mutations can lead to obesity." (PMID 26357660, 2015). "Loss of either peripheral leptin production or central LepRb expression promotes overeating, decreases energy output and leads to severe obesity in rodents and humans, revealing the crucial role of this periphery/brain regulatory system." (PMID 25741247, 2015). "Obesity is associated with decreased leptin transport across the blood–brain barrier in rats and in humans, which explains why obese humans have low CSF leptin levels despite having high-serum leptin levels." (PMID 26236282, 2015). "The same group showed that daily injection of a pegylated leptin antagonist predisposed rats to obesity, promoted leptin resistance and modified the hypothalamic miRNA expression profile." (PMID 25999818, 2015). "Very few studies have evaluated the association of LTL with obesity/diabetes-related biomarkers such as leptin, adiponectin, or insulin, glucose or HOMA scores." (PMID 26380096, 2015). "Animal studies have established that ad libitum access to a high-fat diet promotes hyperphagia and obesity and is associated with leptin and insulin resistance." (PMID 26365669, 2015). "Altered leptin concentrations can be also observed in shift workers and this is associated with diminished satiety and obesity." (PMID 26000016, 2015). "Two potential mechanism underlying impaired renal function in obesity are glomerular hyperfiltration and leptin-mediated glomerular injury." (PMID 25710704, 2015). "Conversely in anorexigenic pro-opiomelanocortin POMC neurons, Mfn2 selective deletion causes severe obesity and leptin resistance probably by mediating ER stress-induced leptin resistance." (PMID 25904870, 2015). "As a consequence of leptin anorexigenic function, leptin-deficient (ob/ob) or leptin receptor-deficient (db/db) mice display a phenotype of hyperphagia and obesity [see reviews in Ref." (PMID 26042085, 2015). "In recent years, it has become clear that obesity can be associated with disturbed hypothalamic control of adiposity signaling peptides, such as leptin." (PMID 26371051, 2015). "Leptin levels are directly associated with adipose tissue mass, while adiponectin levels are downregulated in obesity." (PMID 26064110, 2015). "Recently, stearoyl-coenzyme A desaturase-1 (SCD1) down-regulation has been implicated in the prevention of obesity and in the improvement of insulin and leptin sensitivity." (PMID 25871295, 2015). "In model 3, for leptin levels, significant positive associations were noted with gender (P = 0.011), overweight (P < 0.001), obesity (P < 0.001) and HOMA-IR (P = 0.002)." (PMID 26581745, 2015). "With aging, there is a concomitant increase in the levels of serum leptin, proinflammatory cytokines that are linked to obesity, and the prevalence of metabolic diseases." (PMID 26473487, 2015). "Leptin, the gene product of the obesity gene, is directly associated with the regulation of adipose tissue mass and body weight in humans and rodents." (PMID 26474757, 2015). "The ZDF rat is the most commonly used leptin deficient rat model of metabolic syndrome, obesity, and diabetes." (PMID 25961053, 2015).